TANGO2 (transport and golgi organization 2 homolog)
Description:
May be involved in lipid homeostasis.
Synonyms: C22orf25; DKFZp761P1121; MECRCN
Tractability: PROTAC: its protein half-life has been measured.
Gene: Protein-coding gene on chromosome 22 (20,016,615 to 20,067,164, forward strand). Ensembl gene ENSG00000183597.
Subcellular location: Cytoplasm; Mitochondrion; Golgi apparatus
Gene Ontology:
Molecular function: protein binding
Biological process: Golgi organization; protein secretion
Cellular component: cytoplasm; cytosol; Golgi apparatus; mitochondrion
Genetic constraint (gnomAD): Loss-of-function variants: 20 observed, 31.79 expected, observed/expected ratio (o/e) 0.63, 90% interval 0.44 to 0.91. The upper end of that interval is the gene's LOEUF score, 0.91, which puts it in group 3 of 6, group 1 being the genes least tolerant of losing a copy. Missense variants: 310 observed, 340.26 expected, observed/expected ratio (o/e) 0.91, 90% interval 0.83 to 1. Synonymous variants: 123 observed, 132.74 expected, observed/expected ratio (o/e) 0.93, 90% interval 0.8 to 1.08.
Homologues: Orthologues: chimpanzee TANGO2 (93% identical), macaque TANGO2 (92% identical), dog TANGO2 (91% identical), rabbit TANGO2 (88% identical), mouse Tango2 (88% identical), guinea pig TANGO2 (87% identical), rat Tango2 (87% identical), pig TANGO2 (74% identical), tropical clawed frog tango2 (67% identical), zebrafish tango2 (63% identical), Drosophila melanogaster Tango2 (31% identical), Caenorhabditis elegans hrg-9 (31% identical), and 1 more.
Diseases named in the same sentence as TANGO2 in open-access papers:
TANGO2 is named in the same sentence as 40 diseases in open-access papers, as found by Europe PMC text mining. Sharing a sentence is not in itself a finding about the gene and the disease. The quoted sentences say what the papers report.
Arrhythmia (13 papers, 2020 to 2025). Any cardiac rhythm other than the normal sinus rhythm. "Mutations in the TANGO2 gene cause an autosomal recessive disorder characterised by developmental delay, stress-induced episodic rhabdomyolysis, and cardiac arrhythmias along with severe metabolic crises." (PMID 40480980, 2025). "Mutations in this gene are responsible for TANGO2-related metabolic encephalopathy and arrhythmias, an autosomal recessive recurrent metabolic encephalomyopathic crises, rhabdomyolysis, cardiac arrhythmia, and intellectual disability syndrome (OMIM 616878)." (PMID 36980952, 2023). "Bi-allelic truncating mutations in this gene have been associated with TANGO2-related metabolic encephalopathy and arrhythmias presenting with recurrent muscle weakness with rhabdomyolysis, metabolic crises, and cardiac arrhythmia." (PMID 36980952, 2023). "Our findings help explain the physiological consequence of mutations in TANGO2 that induce acute metabolic crises, including rhabdomyolysis, cardiomyopathy, and cardiac arrhythmias, often leading to fatality upon starvation and stress." (PMID 36961129, 2023). "Mutations in TANGO2 result in metabolic encephalopathy and arrhythmias and these conditions are exacerbated upon nutrient starvation, often leading to fatality ⁠." (PMID 36961129, 2023). "The differences we observed are unlikely to be associated with either the pathophysiology of TANGO2 deficiency or folate’s effect on arrhythmia in TANGO2 deficiency; they are more likely to be attributed to the different genetic backgrounds in TAN016 and TAN002." (PMID 38855866, 2024). "TANGO2 deficiency is a rare condition that often presents with arrhythmias but may be unfamiliar to many cardiologists and electrophysiologists." (PMID 38808169, 2024). "Regarding this rare inherited condition, recent research has advanced our understanding by reporting on a cohort of young patients presenting with cardiac crisis, including cardiac arrhythmias and cardiomyopathy during TANGO2 deficiency-related metabolic crises." (PMID 39665114, 2024). "Based on our data, we propose that TANGO2 functions in lipid homeostasis at the level of acyl-CoA metabolism, and defects in lipid metabolism are the main cause of starvation-induced acute rhabdomyolysis, cardiomyopathy, and cardiac arrhythmias." (PMID 36961129, 2023). "In contrast, the TAN016+Ad-WT showed normal rhythm without prolonged FPD/cFPD and EDs, confirming that the arrhythmias seen in the TAN016+Ad-GFP were indeed due to the loss of TANGO2 function." (PMID 38855866, 2024). "Mutations in transport and Golgi organization 2 homolog (TANGO2) have recently been described as a cause of an autosomal recessive syndrome characterized by episodes of metabolic crisis associated with rhabdomyolysis, cardiac arrhythmias, and neurodegeneration." (PMID 36636595, 2023). "However, the TANGO2 gene is not included in most comprehensive arrhythmia and cardiomyopathy panels." (PMID 38808169, 2024).
rhabdomyolysis (9 papers, 2020 to 2025). Necrosis or disintegration of skeletal muscle often followed by myoglobinuria. "TANGO2, another gene in this group, has gained significant attention due to its association with neurodevelopmental delay, hypothyroidism, rhabdomyolysis, and cardiomyopathy with life-threatening arrhythmias." (PMID 40015245, 2025). "Patients with pathogenic variants in the TANGO2 gene suffer from severe and recurrent rhabdomyolysis episodes precipitated by fasting." (PMID 39722856, 2024). "This is similar to many TANGO2-deficient patients that exhibit normal motor function except for the development of acute muscle damage during rhabdomyolysis episodes." (PMID 37577943, 2023). "These insights may provide new avenues for addressing the severe cardiomyopathies and rhabdomyolysis associated with defective TANGO2 in humans." (PMID 40015245, 2025). "A rhabdomyolysis and metabolic myopathy gene panel (Invitae) was obtained inpatient and ultimately identified a pathogenic multiexon deletion of exons 3–9 and a second variant of uncertain significance (c.187G > T; p.Gly63Cys) in the TANGO2 gene." (PMID 40687628, 2025). "TANGO2 deficiency in patients is associated with rhabdomyolysis." (PMID 37577943, 2023). "Similarly, human TANGO2-deficient patients have variable rhabdomyolysis onset, which may be caused by differences in behavior or metabolic processes." (PMID 37577943, 2023). "This is similar to TANGO2-deficient patients, who typically do not exhibit early embryonic developmental defects and develop metabolic crises and rhabdomyolysis during early or late childhood." (PMID 37577943, 2023).
cardiomyopathy (5 papers, 2023 to 2025). A disease of the heart muscle or myocardium proper. "Mutations in the TANGO2 gene cause severe cardiomyopathies and rhabdomyolysis, particularly under stress." (PMID 40015245, 2025). "The most profound defects manifested as cardiomyopathy, liver steatosis, and impaired cytoskeletal architecture in the heart and skeletal muscle, that is also commonly found in patients with TANGO2 mutations, including rhabdomyolysis." (PMID 40480980, 2025). "Now that we know TANGO2 is an acyl-CoA binding protein, this discovery should help explain why the loss of TANGO2 function leads to severe conditions like cardiomyopathy and rhabdomyolysis." (PMID 40015245, 2025).
Hypoglycemia (4 papers, 2019 to 2024). A decreased concentration of glucose in the blood. "TANGO2 mutations at 22q11.2 have been associated with metabolic abnormalities such as hypoglycemia, as well as epilepsy, and our PheWAS for TANGO2 showed abnormal glucose (P = 0.0013) and epilepsy, recurrent seizures, and convulsions (P = 0.0049) as top phenotypes." (PMID 34715901, 2021). "Additional episodic metabolic abnormalities including ketosis, hypoglycemia, and lactic acidosis prompted further analysis of TANGO2, which lies within the 22q11 deletion region." (PMID 30245509, 2019).
Encephalopathy (3 papers, 2020 to 2026). Encephalopathy is a term that means brain disease, damage, or malfunction. "BACKGROUND: TANGO2 deficiency is a rare inherited metabolic disorder characterized by recurrent metabolic crises, rhabdomyolysis, arrhythmias, and encephalopathy." (PMID 41913275, 2026). "Mutations in human TANGO2 can cause an inherited disease, which exhibits pleiotropic symptoms, including developmental delay, rhabdomyolysis, arrhythmias, encephalopathy, and metabolic crisis." (PMID 37509184, 2023).
hypothyroidism (3 papers, 2023 to 2024). Abnormally low levels of thyroid hormone. "TANGO2 deficiency explains the initial presentation of myositis, rhabdomyolysis, hypothyroidism, and life-threatening arrhythmias surrounding a viral illness more so than the initial diagnosis of mere LQTS." (PMID 38808169, 2024). "TANGO2 mutations and deficiency are associated with a variety of symptoms including hypothyroidism, metabolic and cardiac dysfunction, and rhabdomyolysis." (PMID 37234859, 2023).
ventricular fibrillation (3 papers, 2017 to 2024). A disorder characterized by an electrocardiographic finding of a rapid grossly irregular ventricular rhythm with marked variability in QRS cycle length, morphology, and amplitude. "TANGO2 deficiency disorders may present as ventricular fibrillation storms requiring multiple treatment approaches including high dose of vitamins and supplements, multiple antiarrhythmics and innovative approaches including sympathetic denervation." (PMID 39665114, 2024).
epilepsy (2 papers, 2021 to 2024). A brain disorder characterized by episodes of abnormally increased neuronal discharge resulting in transient episodes of sensory or motor neurological dysfunction, or psychic dysfunction. "On the epilepsy panel of genetic testing, he was found to have two pathogenic variants in TANGO2." (PMID 38808169, 2024).
prostate carcinoma (2 papers, 2017 to 2019). A carcinoma that arises from epithelial cells of the prostate gland. "In humans, a germ line truncation variant of TANGO2 is associated with increased risk of prostate cancer." (PMID 30890123, 2019). "Previously unpublished survival analysis of TANGO2 protein expression in human prostate cancer is consistent with a tumor suppressor role." (PMID 30890123, 2019).
22q11.2 deletion syndrome (1 paper, 2024). 22q11.2 deletion syndrome (DS) is a chromosomal anomaly which causes a congenital malformation disorder whose common features include cardiac defects, palatal anomalies, facial dysmorphism, developmental delay and immune deficiency. "Our study may also have implication on the 22q11.2 deletion syndrome where the region of recurrent microdeletions may include the part of the whole TANGO2 gene body in certain patients." (PMID 38855866, 2024).
Acidosis (1 paper, 2021). Abnormal acid accumulation or depletion of base. "FGA identified 36 kb deletions disrupting TANGO2 (OMIM #616878, case 5103) in siblings with a history of episodic rhabdomyolysis, metabolic acidosis, and ketosis." (PMID 34556655, 2021).
Desminopathy (1 paper, 2025). "We show that the pathogenic R120G mutation in CRYAB impairs its interaction with TANGO2, providing an additional molecular insight into the pathogenic mechanisms by which this mutation causes a desminopathy in patients." (PMID 40480980, 2025). "Our data show that TANGO2 is required for CRYAB activity and intermediate filament structure as its loss leads to a desminopathy that is consistent with those identified in patients carrying desmin and CRYAB mutations." (PMID 40480980, 2025). "In the absence of TANGO2, reduced levels of desmin lead to desminopathy in mice and in patient cells with a TANGO2 mutation." (PMID 40480980, 2025). "However, a mutation that causes familial desminopathy (R120G), producing high molecular weight protein aggregates and loss of the chaperone activity of the protein in vitro, prevented the interaction between CRYAB and TANGO2." (PMID 40480980, 2025). "Therefore, TDD may be considered a sub-class of desminopathy and TANGO2 mutations could be screened in the clinic when patients present with a desminopathy that is not caused by desmin or CRYAB mutations." (PMID 40480980, 2025).
Epileptic encephalopathy (1 paper, 2026). A condition in which epileptiform abnormalities are believed to contribute to the progressive disturbance in cerebral function.
Glucose intolerance (1 paper, 2025). Glucose intolerance (GI) can be defined as dysglycemia that comprises both prediabetes and diabetes. "In male mice, loss of TANGO2 caused heart defects, reduced muscle function and glucose intolerance by remodelling of intermediate filaments, which altered the mitochondrial and cytoplasmic proteomes, N-glycosylation and nucleocytoplasmic O-GlcNAcylation." (PMID 40480980, 2025).
Insulin resistance (1 paper, 2025). Increased resistance towards insulin, that is, diminished effectiveness of insulin in reducing blood glucose levels. "The Tango2–/– mice were glucose intolerant, developed insulin resistance and had increased circulating levels of insulin on both diets." (PMID 40480980, 2025).
Intellectual disability (1 paper, 2024). "One of the variants, rs2531698, is an intronic variant within ARVCF, located in 2 kb upstream of the TANGO2 gene, which is associated with neurodegeneration and intellectual disability." (PMID 39429782, 2024).
metabolic myopathies (1 paper, 2017). "While biallelic disruptions of TANGO2 have been reported to cause pediatric metabolic myopathies, the function of TANGO2 remains unknown and the metabolic phenotype is ascribed to the loss of the other TANGO2 isoforms that are not altered by the TANGO2 p.Ser17Ter variant described here." (PMID 27902461, 2017).
microtia (1 paper, 2023). "Further study is needed to assess the contribution of TANGO2 to microtia and CHD, which is involved in the 22q11.2 phenotypic spectrum." (PMID 37107637, 2023).
osteosarcoma (1 paper, 2019). A usually aggressive malignant bone-forming mesenchymal neoplasm, predominantly affecting adolescents and young adults. "Exome-sequencing in canine osteosarcoma showed TANGO2 has the third highest rate of somatic sequence mutation." (PMID 30890123, 2019).
Ventricular arrhythmia (1 paper, 2024). "TANGO2 deficiency is a rare but important disease that should be considered in patients presenting in an acute metabolic crisis with life-threatening recalcitrant ventricular arrhythmias." (PMID 38808169, 2024).
infection (1 paper, 2023). The state of being infected such as from the introduction of a foreign agent such as serum, vaccine, antigenic substance or organism. "To avoid potential artefacts from an uneven or abnormal protein expression by transient transfection, we generated stable cell lines expressing low levels of the C-terminally EGFP-tagged TANGO2 using lentiviral infection ⁠." (PMID 36961129, 2023).
mitochondrial disease (1 paper, 2023). "Another CNV-associated superenhancer region identified in our data set was TANGO2, a Golgi system-associated protein coding gene mainly associated with mitochondrial disease." (PMID 37216666, 2023).
TANGO2 also shares sentences with these, for which no sentence is quoted: cardiac arrhythmias (6 papers); intellectual disability syndrome (2); lactic acidosis (2); metabolic disorder (2); tumor (2); aggressive (1); autism (1); brain malformations (1); cancer (1); cognitive decline (1); developmental delay (1); diseases of the larynx and vocal cords (1); Hypercholesterolemia (1); mitochondrial myopathies (1); myositis (1); Myotonia (1); neurological diseases (1); schizophrenia (1).